WWOX (WW domain containing oxidoreductase)
Diseases named in the same sentence as WWOX in open-access papers (continued):
Sharing a sentence is not in itself a finding about the gene and the disease.
microcephaly (12 papers, 2014 to 2023). A congenital or acquired developmental disorder in which the circumference of the head is smaller than normal for the person's age and sex. "As in Wwox knockout mouse models, a homozygous WWOX nonsense mutation caused growth retardation, microcephaly and early death in a patient from a consanguineous family." (PMID 32000863, 2020). "Thus, mutations in the WWOX gene have led to developmental delay, microcephaly, recurrent seizures, and motor dysfunction, but mutations in different parts of the gene have resulted in varying severity and type of motor dysfunction (spasticity and hypotonia)." (PMID 34540776, 2021). "Notably, null mutations of WWOX/Wwox gene in humans and animals lead to severe neural diseases (e.g., microcephaly, seizure, ataxia, etc.), growth retardation, metabolic disorders, developmental delay, and early death." (PMID 27999774, 2016). "In two families, early death with microcephaly, epileptic seizures, growth retardation and eye abnormalities (retinopathy and optic atrophy) result from homozygous early premature termination codons in WWOX gene." (PMID 27495153, 2016).
glioma (11 papers, 2013 to 2025). A benign or malignant brain and spinal cord tumor that arises from glial cells (astrocytes, oligodendrocytes, ependymal cells). "Low-grade glioma (from which IDH-mutated GBM could arise) was included in the analysis to determine whether WWOX loss might also switch expression profile at the earlier stages of carcinogenesis; this may potentially lead to an improved on-time diagnosis." (PMID 34204789, 2021). "Very interestingly, we previously identified that deletion genotypes of CNV-67048 in WWOX gene predispose their carriers to gliomas, which are the most common primary tumors of the central nervous system (CNS) and representing more than 80% of all malignant brain tumors." (PMID 26910372, 2016). "In gliomas, we documented brain-specific immunomodulatory impact of the WWOX/HIF1A axis, which is also context-dependent." (PMID 41007296, 2025). "A functional CNV (CNV-67048) of human WW domain-containing oxidoreductase (WWOX), which has been identified as a tumor suppressor gene in multiple cancers, was identified to be associated with gliomas risk previously." (PMID 26910372, 2016). "Moreover, WWOX overexpression was shown to promote the immune response in a glioma model while FHIT positively regulates expression of MHC class I molecules on cancer cells." (PMID 26375816, 2015). "For GBM, it has been found that WWOX downregulation may be a result of promoter hypermethylation or loss of heterozygosity (LOH); the latter is related to tumor progression and contributes to 20% of gliomas." (PMID 34204789, 2021). "The RNA-binding protein, HNRNPA2B1, can regulate the splicing of many tumor suppressor genes in glioma, such as RON, BIN1, WWOX, and c-FLIP." (PMID 32272554, 2020). "For example, HNRNPA2B1 could enhance the expression of the oncogenic isoforms of many tumor suppressor genes (e.g., RON, BIN1, WWOX, and c-FLIP) in glioma by modulating the splicing of these genes, thereby promoting glioma progression and aggressiveness." (PMID 34745938, 2021). "Although the role of WWOX in the cytoskeleton rearrangement has been found in neural progenitor cells, its function as a modulator of cytoskeleton in gliomas was not investigated." (PMID 34204789, 2021).
triple-negative breast carcinoma (10 papers, 2018 to 2025). An invasive breast carcinoma which is negative for expression of estrogen receptor (ER), progesterone receptor (PR), and human epidermal growth factor receptor 2 (HER2). "WW domain-containing oxidoreductase (WWOX) loss frequently occurs in triple-negative breast cancer (TNBC)." (PMID 39473747, 2024). "WWOX deficiency has a role in the expression of the estrogen receptor and is associated with triple-negative breast cancer." (PMID 35460704, 2022). "WWOX deficiency leads to the activation of JAK2/STAT3 signaling in metastatic triple negative breast cancer cells." (PMID 34140629, 2021). "Loss of WWOX in triple-negative breast cancer cells leads to activation of the JAK2/STAT3 pathway for metastasis." (PMID 31123603, 2019). "Loss of WWOX upregulates the JAK2/STAT3 pathway for driving cancer metastasis in triple negative breast cancer cells." (PMID 31123603, 2019). "Loss of WWOX upregulates the JAK2/STAT3 pathway that drives cancer metastasis in triple negative breast cancer cells." (PMID 31315632, 2019). "For instance, the downregulation of WWOX expression is associated with increased tumor grade and aggressiveness, along with lower recurrence-free and overall survival rates in patients diagnosed with Basal-like and Triple-Negative Breast Cancer." (PMID 41228229, 2025). "A recent study in our lab demonstrated that WWOX suppresses Myc levels and activity in triple-negative breast cancer cell lines, by which WWOX binds the Myc transcription factor on the chromatin and modulates its activity on target genes." (PMID 38182577, 2024). "WWOX also regulates the expression of microRNA in the control of metastasis of triple negative breast cancer cells." (PMID 34140629, 2021). "In parallel, a recent study showed that WWOX restricts the migration of triple negative breast cancer cells via regulating the expression of miR-146a." (PMID 31315632, 2019). "Furthermore, WWOX, a negative regulator of c-Myc, has been demonstrated to inhibit the FN expression level and metastatic ability of triple-negative breast cancer (TNBC) by upregulating miR-146a." (PMID 33248456, 2020). "Recently, we reported that WW domain-containing oxidoreductase (WWOX) acts as a tumor suppressor and has anti-metastatic activities involving regulation of several key microRNAs (miRNAs) in triple-negative breast cancer (TNBC)." (PMID 32300104, 2020). "In particular, it has been shown that WWOX protein levels are reduced or absent in triple-negative breast cancer (TNBC) and in BLBC10–15." (PMID 30082886, 2018).
colon carcinoma (9 papers, 2012 to 2024). "In our present study, we observed WWOX-dependent changes in proliferation and apoptosis in two colon cancer cell lines HT29 and SW480, which vary in terms of epithelial-mesenchymal transition (EMT) markers, WNT activity and stemness signatures." (PMID 24938873, 2014). "For example, focal deletions of RBFOX1 (16p13 locus) are present in both cancer types, while WWOX (16q24 locus) deletions are only visible for colon cancers." (PMID 24684958, 2014). "We have noticed reduction of proliferation rate and adhesion to ECM proteins in SW480 colon cancer cell line overexpressing WWOX, which observations seem to confirm the well-described tumour suppressor properties of WWOX gene." (PMID 24938873, 2014). "Overall, WWOX overexpression resulted in similar genomic modifications in both colon cancer cell lines except for the TGF-β pathway, apoptosis and proliferation." (PMID 24938873, 2014). "Further studies ought to be conducted in order to specify the role of the WW-domain-containing oxidoreductase gene in the process of colon cancer formation." (PMID 24938873, 2014). "For both modified colon cancer cell lines, the expression of multiple genes was found to be altered as a result of WWOX overexpression." (PMID 24938873, 2014). "Additionally, overexpression of WWOX led to a decrease in cell viability of colon cancer cell line SW480 which complement our observations for silenced WWOX variant." (PMID 33691672, 2021). "Besides, the expression level of WWOX is different in two different colon cancer cell lines, which are the HT29 and SW480 cell lines." (PMID 30781701, 2019). "Our results demonstrate for the first time that TRAIL-induced cell death regulation by ezrin in colon carcinoma cells requires WWOX and occurs downstream of the TRAIL DISC, through regulation of ezrin phosphorylation on serine 66, owing to TRAIL's ability to induce PKA activation." (PMID 26010871, 2015). "Increased WWOX mRNA and protein expression was identified in both colon cancer cell lines." (PMID 24938873, 2014). "Specifically, we targeted large genes PRKG1, NEGR1, and MAGI2 in fibroblast line UM-HF1 (HF1) and FHIT and WWOX in lymphoblastoid line GM12878 and colon cancer line HCT116 as model systems for replication stress-associated SV formation." (PMID 39505880, 2024). "Deficiency in WWOX expression in the liver cancer SK-HEP1 or the pancreatic Mia PaCa-2 cell lines as well as WWOX silencing or modulation of PKA activation by pharmacological regulators, in the colon cancer cell line SW480, abrogated regulation of TRAIL signalling by ezrin." (PMID 26010871, 2015). "Interestingly, the only gene contained within the 16 q23.1 locus is the WWOX tumor suppressor, an inhibitor of the WNT/beta-catenin pathway, which is frequently activated in colon cancer." (PMID 22860045, 2012). "Our observations suggest that in the HT29 colon cancer cell line, increased expression of WWOX may result in the transition of cancer cells into a more normal colon epithelium phenotype, while in SW480, WWOX demonstrated well-known tumour suppressor properties." (PMID 24938873, 2014). "However, no WWOX-induced changes were observed in the transcription of apoptosis-related genes (BAX, BCL2, BIRC5), whose expression was observed to correlate with WWOX in colon tumour specimens and other cancer tissues." (PMID 24938873, 2014).
gastric cancer (9 papers, 2006 to 2026). A primary or metastatic malignant neoplasm involving the stomach. "The T allele decreases the binding affinity of NR3C1, resulting in reduced WWOX expression, which subsequently lowers the survival rate of gastric cancer patients." (PMID 41228229, 2025). "Another study observed that in vitro gastric cancer cell lines infected with H. pylori showed increased methylation in the WWOX gene." (PMID 38140282, 2023). "TMEM207 binding with the WW domain-containing oxidoreductase promotes cell migration and invasion in gastric cancer." (PMID 26056045, 2015). "Previous studies implicate WWOX in the development of gastric carcinoma, suggesting that additional effects of wwox dysregulation may be associated with the present zebrafish phenotype." (PMID 25649963, 2015). "FHIT loss, with or without WWOX loss, has been shown to correlate positively with tumor invasiveness and prognosis in several cancers (breast, pancreas, gastric cancers)." (PMID 16895604, 2006). "A similar percentage of WWOX gene LOH was also observed in pancreatic primary tumors (27%), gastric carcinoma (31%) and primary non-small cell lung cancer samples (37%)." (PMID 25295115, 2014).
autosomal recessive spinocerebellar ataxia 12 (8 papers, 2020 to 2025). "WWOX pathogenic biallelic variants are implicated in a spectrum of neurological phenotypes, ranging between autosomal recessive spinocerebellar ataxia type 12 (SCAR12; MIM 614322) to the most severe WOREE syndrome." (PMID 32581702, 2020). "Autosomal recessive spinocerebellar ataxia-12 (SCAR12) phenotype organoids showed similar results, indicating cortical origins of the WWOX deficiency." (PMID 39062993, 2024). "Biallelic mutations in WWOX are responsible for early infantile epileptic encephalopathy-28 (EIEE28; OMIM 616211) and autosomal recessive spinocerebellar ataxia-12 (SCAR12; OMIM 614322)." (PMID 32081867, 2020).
developmental delay (8 papers, 2016 to 2023). "In patients with early infantile epileptic encephalopathy with refractoriness to ASMs and global developmental delay associated with characteristic neuroradiological patterns, the WWOX gene analysis should be included in the diagnostic workup." (PMID 38161429, 2023). "Using Whole Exome Sequencing (WES), a novel homozygous mutation in the WWOX gene is identified in a consanguineous Arab family from Qatar with two daughters who presented with intractable seizure and developmental delay." (PMID 27495153, 2016).
leukemia (8 papers, 2004 to 2022). A malignant (clonal) hematologic disorder, involving hematopoietic stem cells and characterized by the presence of primitive or atypical myeloid or lymphoid cells in the bone marrow and the blood. "The event involves a newly identified IκBα/WWOX/ERK signaling to drive leukemia cell differentiation, in which WWOX phosphorylation at Ser14 is required." (PMID 34359949, 2021). "For example, ionophore/phorbol ester-mediated forced differentiation of leukemia T cells or normal T cells requires WWOX phosphorylation at Ser14, but dephosphorylation at pY33 and pY61." (PMID 32764489, 2020). "Forced T leukemia cell differentiation by calcium ionophore and phorbol ester requires rapid de-phosphorylation of WWOX at Y33 and Y287 but increased phosphorylation at S14 in less than five minutes." (PMID 32764489, 2020). "WWOX binds MEK, and that PMA dissociates this complex for causing apoptosis of T leukemia cells." (PMID 23459853, 2013).
neuroblastoma (8 papers, 2009 to 2022). Neuroblastoma (NB) is the most common solid, extracranial childhood tumor. "This was followed by knockdown of WWOX in the human neuroblastoma cell line (SK-N-SH cells) using small interfering RNA (siRNA)." (PMID 34831305, 2021). "Later on, research in SH-SY5Y neuroblastoma cells showed that WWOX physically interacts with and inhibits GSK-3β, preventing Tau hyperphosphorylation." (PMID 34831305, 2021). "In vitro analysis revealed that knockdown of WWOX protein in neuroblastoma cells results in aggregation of TRAPPC6AΔ, TIAF1, amyloid β, and Tau in a sequential manner." (PMID 30158849, 2018). "Additionally, enrichment was seen in genes related to neuron fate commitment and specification, supported by the work in neuroblastoma cell lines that connected WWOX to GSK-3β and neuronal differentiation." (PMID 34831305, 2021). "WWOX has been shown to interact with and inhibit GSK3β, thereby increasing the microtubule assembly activity of Tau and promoting neurite outgrowth in human neuroblastoma SH-SY5Y cells." (PMID 32000863, 2020). "The second important finding is that as an inducer of PD, neurotoxin MPP+ rapidly increases WWOX phosphorylation at Tyr33 and upregulates the expression of TPC6AΔ, followed by TIAF1, SH3GLB2, Aβ, and tau in neuroblastoma SK-N-SH cells." (PMID 36498839, 2022). "WWOX was shown to interact with JNK1 in both MPP+-treated neurons and neuroblastoma SK-N-SH cells." (PMID 34831305, 2021). "Consequently, WWOX represses GSK-3β activity in hyperphosphorylating tau, restores tau’s ability to assemble the microtubule network, and promotes neurite outgrowth in neuroblastoma SH-SY5Y cells." (PMID 30158849, 2018).
spinocerebellar ataxia type 12 (8 papers, 2020 to 2025). Spinocerebellar ataxia type 12 (SCA12) is a very rare subtype of type I autosomal dominant cerebellar ataxia (ADCA type I). "WWOX biallelic germline pathogenic variants have been implicated in spinocerebellar ataxia type 12 (SCAR12; MIM:614322) and in early infantile epileptic encephalopathy (EIEE28; MIM:616211)." (PMID 33255508, 2020). "Interestingly, the WWOX protein is mostly expressed in the cerebellar cortex and in specific cell types, such as basket cells and granule cells, and hypomorphic mutations of WWOX have been associated with cerebellar disorders such as Spinocerebellar Ataxia Type 12 (SCAR12) (MIM: 614322)." (PMID 38161429, 2023).
head and neck squamous cell carcinoma (6 papers, 2015 to 2025). A squamous cell carcinoma that arises from any of the following anatomic sites: lip and oral cavity, nasal cavity, paranasal sinuses, pharynx, larynx, and salivary glands. "In head and neck squamous cell carcinoma (HNSCC), miR-134 expression was reversely associated with the WWOX expression in clinical HNSCC tissues and miR-134 directly targets the 3′ UTR of WWOX gene in HNSCC cells." (PMID 34948746, 2021). "Inactivation of WWOX gene participates in the progression of head and neck squamous cell carcinoma (HNSCC)." (PMID 28045433, 2017). "In head and neck squamous cell carcinoma, it has also been reported that WWOX expression was decreased by miR-134 and promoter methylation." (PMID 27655721, 2016). "Moreover, miR-134 is significantly upregulated in head and neck squamous cell carcinoma (HNSCC) tissues, and its expression is negatively correlated with WWOX levels." (PMID 41228229, 2025).
liver cancer (6 papers, 2015 to 2026). An epithelial or non-epithelial malignant neoplasm that arises from the liver. "In our study, we further delineate the role of WWOX as a tumor suppressor in liver cancer." (PMID 29724996, 2018). "The fact that WWOX expression is reduced in early liver cancer lesions suggests that WWOX may have a role in suppressing liver carcinogenesis." (PMID 29724996, 2018). "Moreover, a study indicated that the expression levels of WW-domain-containing oxidoreductase (WWOX) and hypoxia-inducible factor-1 (HIF-1) may impact the susceptibility of HCC cells to ADI-PEG 20, implying the potential use of these proteins as biomarkers for ADI-PEG 20 in liver cancer treatment." (PMID 37445845, 2023).
metastatic cancer (6 papers, 2013 to 2022). A carcinoma which has spread from the original site of growth to another anatomic site. "Cells which are deficient in WWOX protein, or express dysfunctional WWOX, can be considered as metastatic cancer cells (designated as WWOXd)." (PMID 35883580, 2022). "TGF-β induces WWOX activation via Tyr33 phosphorylation and nuclear translocation to suppress cancer growth, and that loss of WWOX is found in a majority of metastatic cancer cells." (PMID 31315632, 2019). "Promoters for tumor suppressor genes WWOX and Fhit are frequently hypermethylated and silenced in metastatic cancers." (PMID 27234387, 2013). "In parallel with the protein expression of WWOX, TIAF1 is upregulated in developing tumors, but may disappear in established metastatic cancer cells." (PMID 27234387, 2013). "Although the authors showed evidence that WWOX is overexpressed in pre-metastatic cancer, the conclusion that WWOX may play function in tumor progression might not be accurate for the following reasons." (PMID 30619734, 2018).
non-small cell lung carcinoma (6 papers, 2013 to 2022). A group of at least three distinct histological types of lung cancer, including non-small cell squamous cell carcinoma, adenocarcinoma, and large cell carcinoma. "Deletions within the WWOX coding sequence and loss of WWOX expression are observed in many kinds of tumors, for example breast, ovarian and non-small cell lung cancers." (PMID 35328751, 2022). "Ectopic expression of wild type WWOX suppresses the growth human non-small cell lung cancers (NSCLCs) both in cell culture and in patients in a SDR domain-dependent manner." (PMID 27234396, 2013). "WW-domain-containing oxidoreductase (WWOX) is a tumour suppressor gene from the common fragile site FRA16D, whose altered expression has been observed in many tumour types, i.e. breast, gastric, prostate, non-small cell lung cancer and Wilms’ tumours." (PMID 24938873, 2014).